EHF (ETS homologous factor)
Diseases named in the same sentence as EHF in open-access papers (continued):
Sharing a sentence is not in itself a finding about the gene and the disease.
gastric cancer (8 papers, 2016 to 2025). A primary or metastatic malignant neoplasm involving the stomach. "In EBV-associated gastric cancers in particular, EHF was up-regulated through a LMPA2 viral protein-mediated activation of STAT3, which resulted in enhanced cell growth." (PMID 41425714, 2025). "In summary, we found frequent overexpression and amplification of EHF in gastric cancers and revealed a strong association of EHF overexpression/amplification with poor patient outcomes." (PMID 27787520, 2016). "We investigated the association of EHF amplification with clinicopathologic features and clinical outcomes in a cohort of gastric cancers." (PMID 27787520, 2016). "Second, EHF amplification (or overexpression) was significantly associated with poor clinical outcomes and may be used as a potential prognostic marker for gastric cancer patients." (PMID 27787520, 2016). "Moreover, EHF amplification was positively correlated with its overexpression and significantly associated with poor clinical outcomes of gastric cancer patients." (PMID 27787520, 2016). "This research explores the prognostic signature of MAGED2, KEAP1, GLA, EIF1AD, and EHF genes associated with hypoxia in gastric cancer through analyzing transcriptome information and scRNA-seq data, and indicates the clinical relevance of hypoxia during gastric cancer progression." (PMID 40129974, 2025). "Thus, we attempted to determine whether oncogenic role of EHF in gastric cancer is associated with the activation of HER family." (PMID 27787520, 2016). "In vitro experiments have confirmed that knocking down EHF in gastric cancer cells significantly reduces their clonal formation ability, invasion, and migration capacity, leads to cell cycle arrest, decreased proliferation, and increased apoptosis." (PMID 40129974, 2025). "ELF3, together with KLF5 and EHF overexpression, has been shown to characterize a subset of peritoneal metastatic gastric cancers through the induction of super-enhancers." (PMID 41425714, 2025). "On the transcriptional level, HER3 expression in gastric cancer is critically regulated by the transcription factor EHF and overexpression of EHF leads to increased HER3 levels." (PMID 33374770, 2020). "As observed in gastric cancers, EHF mRNA expression correlated with HER2 and HER3 expression in primary PTCs, and EHF was shown to directly bind and transactivate the HER2 and HER3 promoters in PTC cell lines." (PMID 30200227, 2018). "We next evaluated the effect of EHF knockdown on cell cycle distributions and apoptosis in gastric cancer cells." (PMID 27787520, 2016). "To test the relationship between of EHF copy number and its expression, we randomly selected 16 gastric cancer cases with different EHF copies and did immunohistochemistry (IHC) for EHF." (PMID 27787520, 2016). "In this study, we first provided strong evidences supporting the oncogenic activities of EHF in gastric cancer." (PMID 27787520, 2016). "Collectively, these results suggest that EHF contributes to gastric cancer cell metastasis via promoting EMT process." (PMID 27787520, 2016). "Further analysis showed that EHF copy number in gastric cancers was significantly higher than that in control subjects (P<0.0001)." (PMID 27787520, 2016). "Our results demonstrated that EHF was significantly upregulated and frequently amplified in gastric cancer tissues as compared with control subjects." (PMID 27787520, 2016). "We also found that EHF knockdown notably inhibited gastric cancer cell proliferation, colony formation, migration, invasion and tumorigenic potential in nude mice and induced cell cycle arrest and apoptosis." (PMID 27787520, 2016). "As a member of the ETS family, downstream targets/pathways of EHF in gastric cancer remain to be identified." (PMID 27787520, 2016). "In this study, we found frequent EHF overexpression and genomic amplification in gastric cancers, and demonstrated EHF amplification was one of the major mechanisms for its overexpression." (PMID 27787520, 2016).
gastric cancer (continued). "Third, knocking down EHF expression in gastric cancer cells significantly inhibited cell growth and invasiveness." (PMID 27787520, 2016). "EHF downregulation significantly reduced in vitro and in vivo oncogenic potential of gastric cancer cells by regulating HER family of receptor tyrosine kinases." (PMID 27787520, 2016). "To elucidate the role of EHF in gastric carcinogenesis, we tested the growth-suppressive effect by knocking down EHF expression in gastric cancer cell lines AGS, BGC823 and SGC7901 using siRNA approach." (PMID 27787520, 2016). "As expected, EHF knockdown in gastric cancer cells showed significant growth-inhibitory effect by inhibition of cell proliferation and colony formation in vitro and tumorigenic potential in nude mice in vivo." (PMID 27787520, 2016). "The aim of this study was to explore the role of EHF in tumorigenesis and its potential as a therapeutic target in gastric cancer." (PMID 27787520, 2016). "By using quantitative RT-PCR (qRT-PCR), immunohistochemistry (IHC) and fluorescence in situ hybridization (FISH) assays, we investigated the expression and copy number of EHF in a cohort of gastric cancers and control subjects." (PMID 27787520, 2016). "Similarly, we found that EHF expression was higher in gastric cancer cell lines than gastric mucosal epithelial cell line GES-1." (PMID 27787520, 2016). "Although a previous study has reported frequent EHF amplification in gastric cancers, the role and mechanisms of EHF in gastric tumorigenesis remain totally unknown." (PMID 27787520, 2016). "Multivariate cox regression analysis further demonstrated that EHF amplification might be an independent prognostic factor in gastric cancer (HR=2.426; 95% CI=1.474–3.991; P<0.0001)." (PMID 27787520, 2016). "In addition, we found that EHF expression was positively correlated with poor survival in gastric cancer patients (data from the Kaplan–Meier Plotter; P=0.003)." (PMID 27787520, 2016). "Collectively, EHF may be a new transcription factor for HER2 in gastric cancer by binding to a functional EBS within its promoter, and promotes gastric tumorigenesis by activating HER family of receptor tyrosine kinase." (PMID 27787520, 2016). "Collectively, our findings suggest that EHF is a novel functional oncogene in gastric cancer by regulating the human epidermal growth factor receptor (HER) family of receptor tyrosine kinases and may represent a potential prognostic marker and therapeutic target for this cancer." (PMID 27787520, 2016). "In addition, our data showed that EHF amplification dramatically affected patient survival, implicating that it may be used as a potential prognostic marker for gastric cancer patients." (PMID 27787520, 2016). "A better understanding of the physiologic and pathologic function of EHF will significantly improve our knowledge of the pathogenesis of gastric cancer, and targeting this frequently overexpressed/amplified oncogene may elucidate the effective treatment of this cancer in the future." (PMID 27787520, 2016). "mRNA expression levels of ETS family members in gastric carcinoma tissues were variable, with ELF3, ETS2, EHF, ERF, and ELF1 being the family members with the highest expression." (PMID 41425714, 2025). "The level of mRNA expression of ETS family members in gastric carcinoma tissues was also variable with ELF3, ETS2, EHF, ERF and ELF1 being the family members with the highest expression." (PMID 41425714, 2025). "Fourth, EHF was identified to be a new transcription factor of HER2, and also modulated the expression of HER3 and HER4 in gastric cancer." (PMID 27787520, 2016). "EHF knockdown induced cell cycle arrest and apoptosis, and inhibited cell migration, invasion and EMT process in gastric cancer cells." (PMID 27787520, 2016).
gastric cancer (continued). "The family member ELF3 was well expressed in the mRNA level in a subset of gastric cancers (n = 91), and its expression correlated with the expression of other transcription factors involved in gastric cancer pathogenesis, including HNF4A, HNF1A, CDX2, GATA4, GATA6, and EHF." (PMID 41425714, 2025). "KLF5 is also frequently amplified in gastric cancer and has recently been shown to regulate gene expression in OAC in combination with other transcription factors, GATA6, ELF3 and EHF." (PMID 32880368, 2020). "We first examined EHF expression in a cohort of tumor tissues including gastric cancers, gliomas, lung cancers and thyroid cancers and non-cancerous tissues." (PMID 27787520, 2016). "First, EHF was frequently overexpressed and amplified in gastric cancers compared with matched non-cancerous gastric tissues." (PMID 27787520, 2016). "Compared with matched non-cancerous gastric tissues, EHF was significantly upregulated in gastric cancer tissues at both mRNA and protein levels." (PMID 27787520, 2016).
esophageal squamous cell carcinoma (5 papers, 2015 to 2025). Esophageal squamous cell carcinoma (ESCC) is a type of esophageal carcinoma (EC) that can affect any part of the esophagus, but is usually located in the upper or middle third. "Intriguingly, a previous study investigated the role of EHF in esophageal squamous cell carcinoma (ESCC) and found that the altered subcellular location of EHF resulted in ESCC." (PMID 37958443, 2023). "In oesophageal squamous cell carcinoma (ESCC), the primary mechanism of EHF protein dysregulation is altered subcellular localization, where in contrast to its predominantly nuclear expression in the normal oesophageal epithelium, EHF is localized to the cytoplasm." (PMID 30200227, 2018).
lung disease (5 papers, 2015 to 2025). "Here, we show that variation in EHF expression can impact lung diseases through several mechanisms, thereby highlighting prospects for novel therapies." (PMID 40590703, 2025). "Although EHF and APIP are the nearest genes to the intergenic chr11 GWAS locus with significant lung disease association p-values, PDHX is best predicted to be regulated by SNPs in the region based on current gene expression data." (PMID 33253230, 2020). "Our results are relevant to the involvement of both ELF5 and EHF in lung disease, since both genes are expressed in human bronchial epithelium." (PMID 31557407, 2019). "E74‐like factor 5 (ELF5) and ETS‐homologous factor (EHF) are epithelial selective ETS family transcription factors (TFs) encoded by genes at chr11p13, a region associated with cystic fibrosis lung disease severity." (PMID 31557407, 2019). "The fifth locus, on chr11p12-p13 (EHF/APIP; P=1.9 × 10−10), was previously shown to be associated with lung disease." (PMID 26417704, 2015). "Some of these known modifiers are ranked within the top DPMs, including EHF, SFTPA2, and SLC6A14, all previously identified modifiers of lung disease severity in CF." (PMID 33438800, 2020).
lung carcinoma (4 papers, 2016 to 2025). "Among the overlapping target genes, EHF, the expression of which is correlated with increased metastasis of lung cancer cells is by far one of the most downregulated overlapping targets of JMJD6." (PMID 41320721, 2025). "To confirm that EHF is the downstream effector of JMJD6 in radiation-induced lung-cancer metastasis, we transfected shJMJD6 A549 cells with an EHF-overexpression plasmid and monitored cell migration." (PMID 41320721, 2025). "These rescue data demonstrated that JMJD6 promoted lung cancer metastasis predominantly through transcriptional up-regulation of EHF." (PMID 41320721, 2025). "Moreover, EHF was also significantly upregulated in gliomas (P<0.0001), lung cancers (P=0.005) and thyroid cancers (P=0.001) compared with control subjects." (PMID 27787520, 2016).
melanoma (4 papers, 2008 to 2021). A malignant, usually aggressive tumor composed of atypical, neoplastic melanocytes. "In particular, ELK3, ETS1, ETV1, ETV4, ETV5, and SPI1 were significantly upregulated in melanoma, whereas EHF, ELF3, ELF5, ERG, ETS2, ETV7, and SPDEF were significantly downregulated in the tumor." (PMID 33424867, 2020). "Genes such as KRT14, GJA1, S100A7, S100A9, and EHF were higher in most melanomas while genes such as CITED-1, GDF15, QPRT, OCA2, c-MET and MME were more highly expressed in NHEM." (PMID 18442402, 2008).
pancreatic cancer (4 papers, 2022 to 2025). "EHF has been reported as a therapeutic target of rosiglitazone in pancreatic cancer, indicating a promising target for ACP in the future." (PMID 38906852, 2024). "A previous study showed that a low expression of EHF correlates with the promoter methylation in prostate and pancreatic cancer." (PMID 37958443, 2023). "While previous studies have revealed the tumor-promoting role of EHF in thyroid and ovarian cancer, EHF inhibits the invasion and metastasis of pancreatic cancer cells by directly binding to the EBS in the promoter region of the E-cadherin gene and upregulating its expression." (PMID 37958443, 2023).
prostate tumors (4 papers, 2010 to 2019). "Previously we reported that ESE3/EHF is frequently downregulated in prostate tumors and that its loss is associated with robust inflammatory gene signatures." (PMID 27732936, 2016). "Human prostate tumors with IL-6 elevation and loss of ESE3/EHF were associated with STAT3 activation and displayed upregulation of genes related to cell adhesion, cancer stem-like and metastatic spread." (PMID 27732936, 2016). "In prostate tumors, miR-424 is upregulated due to lower expression of ESE3/EHF, which binds to the promoter of miR-424 and represses its transcription." (PMID 30474694, 2019). "Furthermore, we identified a group of prostate tumors that exhibited marked reduction of ESE3/EHF expression in the absence of alterations of other ETS genes, including ERG." (PMID 31143708, 2019).
colorectal cancer (3 papers, 2022 to 2026). A primary or metastatic malignant neoplasm that affects the colon or rectum. "Activates Ets homologous factor (EHF), and EHF knockdown decreases liver metastasis of colorectal carcinoma cells." (PMID 41432313, 2026). "EHF, by activating TGF-b1 transcription and typical TGF-a signal transduction, promotes colorectal cancer progression." (PMID 36578029, 2022).
cystic fibrosis (3 papers, 2018 to 2020). Autosomal recessive disorder caused by pathogenic variants in the CFTR gene (cystic fibrosis transmembrane conductance regulator), which encodes a chloride and bicarbonate channel expressed in epithelial cells, and follow the diagnosis criteria. "EHF has been studied extensively as a potential modifier gene of the severity of the cystic fibrosis phenotype." (PMID 30200227, 2018). "Direct EHF targets in primary human bronchial epithelial cells are enriched for genes involved in lung pathology including EMT and wound response, and knockdown of EHF reduced wound closure in bronchial epithelial cells derived from both healthy and cystic fibrosis patients." (PMID 30200227, 2018).
thyroid cancer (3 papers, 2016 to 2023). "EHF is a context-dependent transcription factor, as it has tumor-promoting role in gastric and thyroid cancer." (PMID 37958443, 2023). "In this study, we first provided evidences suggesting the oncogenic function of EHF in thyroid cancer." (PMID 27517321, 2016). "EHF knockdown significantly inhibited thyroid cancer cell proliferation, colony formation, migration, invasion and tumorigenic potential in nude mice and induced cell cycle arrested and apoptosis by modulating the PI3K/Akt and MAPK/Erk signaling pathways." (PMID 27517321, 2016). "As a member of the ETS family, downstream targets or pathways of EHF in thyroid cancer remain to be identified." (PMID 27517321, 2016). "The aim of this study was to explore the biological functions of EHF and its potential as a therapeutic target in thyroid cancer." (PMID 27517321, 2016). "On the other hand, ectopic expression of EHF in thyroid cancer cells notably promoted cell growth and invasiveness." (PMID 27517321, 2016). "Conversely, EHF overexpression significantly promoted cell growth and invasiveness, further suggesting that EHF possesses a strong tumorigenic function in thyroid cancer." (PMID 27517321, 2016). "The functions of knockdown and ectopic expression of EHF in thyroid cancer cells were determine by a series of in vitro and in vivo experiments." (PMID 27517321, 2016). "EHF knockdown significantly reduced in vitro and in vivo oncogenic potential of thyroid cancer cells by regulating HER family of receptor tyrosine kinases." (PMID 27517321, 2016). "Second, EHF knockdown significantly inhibited tumorigenic potential of thyroid cancer cells, whereas EHF overexpression enhanced the growth and motile/invasive ability of cancer cells." (PMID 27517321, 2016). "To explore the biological roles of EHF in thyroid tumorigenesis, we first chosen thyroid cancer cell lines BCPAP and C643 with high basal levels of EHF for knockdown experiment, and FTC133 and K1 with low basal levels of EHF for overexpression experiment (data not shown)." (PMID 27517321, 2016). "Altogether, our findings suggest that EHF is a novel functional oncogene in thyroid cancer by transcriptionally regulating HER2 and HER3, and may represent a potential therapeutic target for this cancer." (PMID 27517321, 2016). "Altogether, these data suggest the oncogenic function of EHF in thyroid cancer." (PMID 27517321, 2016). "In addition, knockdown or ectopic expression of EHF in thyroid cancer cells significantly reduced or increased mRNA expression of HER2 and HER3, respectively." (PMID 27517321, 2016). "However, in TNBC patients with low EHF expression, the re-induction or modulation of EHF expression by demethylating agents needs to be considered with caution because demethylating agents have broad transcriptional effects and EHF has a tumor promoting role in gastric and thyroid cancers." (PMID 37958443, 2023). "However, the biological roles of EHF in thyroid cancer is largely unknown." (PMID 27517321, 2016). "Third, EHF was identified to be a new transcription factor of HER2 and HER3 in thyroid cancer." (PMID 27517321, 2016).
cholangiocarcinoma (2 papers, 2024 to 2025). A carcinoma that arises from the intrahepatic biliary tree (intrahepatic cholangiocarcinoma) or from the junction, or adjacent to the junction, of the right and left hepatic ducts (hilar cholangiocarcinoma). "EHF plays a crucial role in promoting cholangiocarcinoma (CCA) by activating GLI1 transcription." (PMID 38741887, 2024). "The transcription factor EHF recruits and activates TAMs via the CCL2/CCR2 axis, remodeling the TME, and serves as a potential prognostic biomarker in cholangiocarcinoma." (PMID 41417432, 2025).
esophageal adenocarcinoma (2 papers, 2024). A malignant tumor with glandular differentiation arising predominantly from Barrett mucosa in the lower third of the esophagus. "For instance, in esophageal adenocarcinoma, SEs that are specific to this type of cancer regulate the overexpression of pro-carcinogenic transcription factors like ELF3, KLF5, GATA6, and EHF." (PMID 38443991, 2024).
glioma (2 papers, 2016 to 2021). A benign or malignant brain and spinal cord tumor that arises from glial cells (astrocytes, oligodendrocytes, ependymal cells). "In addition, we constructed the R287* mutant of EHF, which is a nonsense mutation at position 287 deposited in the glioma TCGA dataset." (PMID 33712555, 2021). "In addition, mutations around the L285 position in EHF were also deposited in the glioma TCGA dataset." (PMID 33712555, 2021).
lymph node metastasis (2 papers, 2016 to 2022). "EHF amplification was significantly positively associated with differentiation (P=0.049), lymph node metastasis (P=0.029) and survival status (P=0.001)." (PMID 27787520, 2016).
metastatic tumor (2 papers, 2016 to 2017). "The ETS factor ESE3/EHF is an endogenously expressed ETS factor whose level is higher in normal prostate and decreased in aggressive and metastatic tumors." (PMID 27732936, 2016).